IDH1 (isocitrate dehydrogenase (NADP(+)) 1)
Diseases named in the same sentence as IDH1 in open-access papers (continued):
Sharing a sentence is not in itself a finding about the gene and the disease.
tumor (continued). "The most frequently mutated metabolic genes in human cancer are those encoding the enzymes isocitrate dehydrogenase 1 (IDH1) and IDH2; these mutations have so far been identified in more than 20 tumor types." (PMID 35028610, 2021). "We found that the IDH1 gene was overexpressed in all clinical samples, and the expression level correlates with the grade of the tumor." (PMID 34573317, 2021). "After adjusted clinical factors such as age, gender, tumor grade, race, IDH1, the multivariate Cox regression result showed that radiosensitivity-related risk score was an independent prognostic factor for LGG patients." (PMID 34395274, 2021). "IHC staining results showed that positive-staining of ki-67 decreased after IDH1 overexpression, suggesting that the tumor proliferation ability was reduced." (PMID 33867843, 2021). "In conclusion, tumor-SVZ distance and IDH1 mutation status are the determinants affecting patient outcome." (PMID 34490090, 2021). "After adjustment for WHO grade, ATRX, Ki67 and TERT, the molecular groups of IDH1 and MGMT were independently associated with tumor growth." (PMID 32388499, 2020). "The first study showed that the IDH1 mutation and its inactivation induces hypoxia inducible factor 1 (HIF-1) pathways that are important in tumor growth, inhibition of apoptosis, and cell survival under hypoxic conditions." (PMID 32993063, 2020). "Age, gender, IDH1 status, Bcl2 and Ki67 mean scores and labelling indices revealed significant statistical differences among tumor grades." (PMID 32856872, 2020). "After adjusting for WHO grade, ATRX, Ki67, and MGMT, the IDH1, TERT, and 1p/19q molecular groups were independently associated with tumor growth." (PMID 32388499, 2020). "The aim of this study was to establish and characterize PDCs, single-cell-derived PDCs (scPDCs), and xenografts (PDX) of IDH1-mutant recurrences representing distinct stages of tumor evolution." (PMID 32904945, 2020). "In the same population, the median FLT T/N ratios in IDH1-mutant and IDH1-wildtype tumours were 3.43 (IQR 2.20–5.82) and 7.56 (6.00–12.94), respectively." (PMID 32382870, 2020). "Next, the same Cox regression analysis was repeated including clinical variables, like tumor malignancy, MGMT promoter methylation status, IDH1 mutation status, and patient gender and age (<50 or ≥50 years)." (PMID 33227903, 2020). "The median FLT T/N ratio in IDH1-wildtype tumours was significantly higher than that in IDH1-mutant tumours (P = 0.005)." (PMID 32382870, 2020). "Digital PCR confirmed the presence of wild-type and R132H mutated IDH1 alleles in PDOXs, although variations in ratio were observed probably due to TME signal in patient tumors and tumor aneuploidy (online resource)." (PMID 33009951, 2020). "As a proof of the principal approach, we attempted monitoring of the pan-mutant IDH1 inhibitor BAY1436032 using 1H-MRS to measure tumor 2-HG/tCr ratios in the LNT-229 IDH1-R132H model." (PMID 33138036, 2020). "In fact, AOs (median 5.07, IQR 4.72–7.21) showed increased MET uptake as high as those in GBMs (median 6.19, IQR 4.63–7.41), in which most of them were IDH1-wild type tumours in the present study." (PMID 32382870, 2020). "Of these nine patients, three patients, two patients, and one patient were identified to have an IDH-1 mutation, FGFR-2 fusion, and FGFR-2 mutation in the tumour sample, respectively." (PMID 32899345, 2020). "Immunohistochemistry for IDH1-R132H was done on 5-microns–thick formalin-fixed, paraffin-embedded tumor sections with the use of antibody specific for the mutant IDH1-R132H protein." (PMID 32886667, 2020).
tumor (continued). "The antiproliferative activity of the tested IDH1 inhibitors compared to axitinib and imatinib in several tumor cell lines." (PMID 32110969, 2020). "Again, the median FLT T/N ratio in IDH1-wildtype tumours was significantly higher than that in IDH1-mutant tumours (P < 0.001)." (PMID 32382870, 2020). "Consistently, ectopic expression of IDH1 and pharmacologically increasing intracellular 2-KG can restore the global levels of 5hmC, and consequently, can inhibit tumor growth." (PMID 33282735, 2020). "The median MET T/N ratio in IDH1-wildtype tumours was significantly higher than that in IDH1-mutant tumours (P < 0.001)." (PMID 32382870, 2020). "The mean T/N ratios of MET-PET/CT and FLT-PET/CT in IDH1-wildtype tumours were significantly higher than those in IDH1-mutant tumours (P < 0.001 and P < 0.001, respectively)." (PMID 32382870, 2020). "In the same population, the median FLT T/N ratios in IDH1-mutant and IDH1-wildtype tumours were 1.77 (IQR 1.68–2.33) and 6.00 (4.23–6.38), respectively." (PMID 32382870, 2020). "For IDH1-mutant LGGs in particular, there are few cell lines available that span multiple stages of tumor evolution." (PMID 32904945, 2020). "Equivalent expression of both forms of IDH1 in the presented model remains similar to that described in tumor cells." (PMID 32946483, 2020). "When analysing the uptake values in 13 non-enhancing tumours (9 grade II and 4 grade III) separately, the median MET T/N ratios in IDH1-mutant (n = 10) and IDH1-wildtype (n = 3) tumours were 2.09 (IQR 1.87–3.44) and 3.21 (2.52–3.59), respectively." (PMID 32382870, 2020). "The IDH1, TERT, and 1p/19q; and IDH1 and MGMT molecular groups were independently associated with tumor growth." (PMID 32388499, 2020). "All patients progressed on treatment and only 1 patient with an IDH1-mutant tumor remained alive at last follow-up (34 months)." (PMID 33392506, 2020). "On the other hand, the overlap of FLT T/N ratios between IDH1-mutant and IDH1-wildtype tumours was small." (PMID 32382870, 2020). "Increased MALAT1 expression in IDH1/2 wild-type primary GBs correlated with patient age and tumor localization (p = 0.032 and p = 0.025, respectively)." (PMID 31479414, 2020). "The median FLT T/N ratio in IDH1-wildtype tumours was significantly higher than that in IDH1-mutant tumours (P = 0.028)." (PMID 32382870, 2020). "Molecular groups of IDH1, TERT, and 1p/19q; and IDH1 and MGMT were independently associated with tumor growth." (PMID 32388499, 2020). "Patients with subtype C1 had a remarkably higher histological grade, a greater frequency of wild-type IDH1 in the tumor, and higher stromal scores and immune scores than patients with subtypes C2 and C3, and exhibited poor clinical outcomes." (PMID 33425739, 2020). "In the present study, FLT-PET/CT was able to distinguish the IDH1-mutant tumours from wildtype tumours statistically." (PMID 32382870, 2020). "Given their distinct molecular origins, the optimal treatment strategies for IDH1-mutant versus IDH1-wildtype tumours should be different." (PMID 32382870, 2020). "This is strong evidence of how the immune system in the GBM is robustly activated to be suppressive; indeed, its lack, as in the case of the IDH1-mut patient, leads to a better prognosis and better control of the tumor’s growth." (PMID 32899203, 2020). "The mutant transcript of IDH1 can be detected in EV isolated from CSF, and the quantity of mutant IDH1 transcripts is directly correlated with the tumor volume." (PMID 31979318, 2020). "We confirmed the IDH1-mutation status, as well as high accumulation of 2-HG in the IDH1-mutant tumor by mass spectroscopy." (PMID 32587392, 2020). "It has been reported that GBM has enhanced immune phenotype as compared to lower grades and high tumor purity is a good prognostic marker in IDH1 wild-type GBM38,39." (PMID 30808902, 2019). "SNVs detected in IDHMUT initial (n = 12) and recurrent tumours (n = 1) impacted IDH1 and 10 genes across 5 biological pathways." (PMID 32082376, 2019).
tumor (continued). "We found that Notch3-silenced tumours have significant lower levels of Aco1, Idh1 and Mdh1 than control counterparts." (PMID 30765875, 2019). "In support of this, tumor purity score was found to be the minimum in mesenchymal and IDH1 wild-type GBM subgroups." (PMID 30808902, 2019). "To further identify the relationship between GAS5 expression and overall survival of LGG patients, we first examined GAS5 expression in LGG patients with different IDH1 status, histologic grades, tumour sizes, and histologic types." (PMID 30853980, 2019). "Our results show that IDH1 mutation-mediated effects on redox state and NAD+ homeostasis differ between astrocytes and highly proliferating tumor cells." (PMID 31888244, 2019). "Specifically, IDH1 expression decreases under exposition to the tumor promoters 12-O-tetra-decanoylphorbol-13-acetate (TPA) and ultraviolet C (UVC) irradiation." (PMID 31010244, 2019). "The following logistic regression model was used to establish a diagnostic prediction model that incorporated both age and the tumor volume for joint diagnosis: logit(IDH1) = 2.16674 − 0.13007 × Age + 0.07703 × Tumor volume." (PMID 31275753, 2019). "We performed differential methylation analysis of IDH1/2 mutant tumors comparing six different tumor types." (PMID 31727977, 2019). "In this study, we performed transcriptomic analysis by NGS and revealed that the inhibition of the vascular microenvironment played important roles in tumor growth in the IDH1-mutant GBM xenograft." (PMID 31443404, 2019). "Lastly, the impact of IDH1/2 targeting drugs has been modest so far and has various effects depending on the tumor type suggesting there is a substantial heterogeneity among IDH mutant cancers." (PMID 31727977, 2019). "Mutations in the IDH1 and IDH2 genes have been found in various tumor types and catalyze reduction of a-KG into a structurally similar oncometabolite 2-hydroxyglutarate (2-HG), which probably functions as an α-KG antagonist in numerous metabolic processes." (PMID 31727977, 2019). "IDH1 mutant tumor cells, resulting in an HRD status, are known to be sensitive to olaparib activity, approaching a 50-fold difference compared to IDH1-wt cells." (PMID 31850198, 2019). "Tumor site, both pre-operative and post-operative tumor volumes, ΔVT2T1, EOR, Ki67 expression, IDH1/2 gene mutation, 1p/19q co-deletion, molecular class, and methylation status of the MGMT promoter were associated with PFS at Cox univariate analysis." (PMID 31877896, 2019). "This suggests that IDH1 upregulation represents a metabolic adaptation of GBM to support growing demands of macromolecular synthesis in tumor cells." (PMID 30857299, 2019). "Patients with IDH1-mutant tumors were younger than those with IDH1-wild type tumors, and exhibited a larger tumor volume." (PMID 31275753, 2019). "In this study, we investigated the γδ TCR repertoires in tumor tissues and matched blood from four patients with IDH1 wild-type GBM." (PMID 30967876, 2019). "The high frequent mutations on the single residue (R132 in IDH1, R172 or R140 in IDH2) have caught broad interest in its function in promoting tumor development." (PMID 31591388, 2019). "Accordingly, we observed a shift in the NADPH/NADPt ratio in IDH1-mutant glial cells and tumor cells towards NADP+." (PMID 31888244, 2019).
tumor (continued). "We aimed to assess the intra-tumor hypoxia, angiogenesis and microvessel formation in GBM and to find their associations with IDH1 mutation status and patients prognosis." (PMID 29662659, 2018). "Previously, we found that Glx signal (glutamate + glutamine) by in vivo MRSI is decreased in tumor, compared to contralateral normal appearing white matter in mutant IDH1 patients." (PMID 29662077, 2018). "Tumor tissue obtained at surgery was assessed for IDH1-R132H expression and CD163+ TAM infiltration by immunohistochemistry." (PMID 30400835, 2018). "Using quantitative hMeDIP-PCR on samples where sufficient DNA was available, we confirmed increased 5hmC among an expanded IDH1 mt tumor cohort (n = 25)." (PMID 29428975, 2018). "Low IDH1 expression in tumor was an unfavorable independent predictor for OS and RFS of ccRCC patients (OS, HR, 0.500, 95% CI, 0.253–0.987, p = 0.046; RFS, HR, 0.463, 95% CI, 0.233–0.922, p = 0.028)." (PMID 30153799, 2018). "Thirty-one cfDNA samples positive for IDH1, KRAS, PIK3CA, NRAS, AKT, BRAF, and IDH2 mutations in tumor tissue were selected for ddPCR, MassARRAY and NGS comparison." (PMID 29535804, 2018). "The IDH1 R132H mutation was detected in the tissue samples from 20 GBM patients (38.5%), whereas the IDH1 wild-type tumor was observed in remaining 32 patients (61.5%)." (PMID 29662659, 2018). "In this retrospective multicenter study, we aimed to develop a radiomics model with a minimal set of imaging features from multiple tumor subregions in multiparametric MRI for pretreatment prediction of IDH1 status in GBM patients." (PMID 30426720, 2018). "Examining genes with methylation β-values of ≥ 0.3, the overall contribution of 5hmC to total methylation across the 50-gene list ranged from 7.00 to 17.75% per tumor in IDH1 mt tumors." (PMID 29428975, 2018). "An example in GBM is the mutation (R132H) in the IDH1 gene, which can function as an immunogenic antigen initially recognized by CD4+ T cells, which then progressively lose their anti-tumor function." (PMID 29317703, 2018). "Our data indicated that IDH1 expression level was down-regulated in ccRCC tissues, and it negatively correlated with tumor Fuhrman grade (p = 0.025)." (PMID 30153799, 2018). "At the individual tumor level, mean 5hmC β-values for top 1% probes ranged from 0.139 to 0.301 for IDH1 mt tumors, and 0.082 to 0.211 for IDH1 wt tumors." (PMID 29428975, 2018). "Preclinical characterization of this compound exhibited in vivo correlation of 2-HG reduction and efficacy in a patient-derived IDH1 mutant xenograft tumor model." (PMID 29439493, 2018). "Three multiregional radiomics models were built from tumor core, whole tumor, and all regions using an all‐relevant feature selection and a random forest classification for predicting IDH1." (PMID 30426720, 2018). "This raises the possibility that IDH1 copy number alterations (CNAs) contribute to altering the G-CIMP-low tumor methylome." (PMID 29642018, 2018). "In this study, we detected IDH1 was mainly expressed in the cytoplasm of ccRCC tumor cells, and low expression level of IDH1 in tumor correlated with an adverse outcomes of ccRCC, especially in patients with high SSIGN scores." (PMID 30153799, 2018). "Treatment of IDH1 mutant glioma cells suppressed tumour growth and was effective in inducing differentiation compared to mutant IDH inhibitors." (PMID 30356832, 2018).
tumor (continued). "It showed a higher tumor proportion of centroid #1 (98.6%) in IDH1 mutant tumor and a higher tumor proportion of centroid #2 and centroid #3 (47.6% and 37.9% respectively) in IDH1 wild-type tumor." (PMID 29953478, 2018). "IDH1 expression was predominantly found in the cytoplasm of tumor cells, with variable staining intensity in different specimens." (PMID 30153799, 2018). "IDH1 prediction results with area under the operating characteristic curve (AUC) values of 87.3% and 77.2% were obtained using the features of relative tumor blood flow and necrosis area, respectively." (PMID 28710497, 2017). "Mutations in both IDH1 and IDH2 are ubiquitously expressed within the tumour tissue; moreover, they consistently occur in a heterozygous manner and are most commonly observed in the IDH1 isoform." (PMID 28629182, 2017). "Multiple studies concluded that oncometabolites (e.g. D-2-hydroxyglutarate (2-HG) related to mutant isocitrate dehydrogenase 1/2 (IDH1/2) and lactate) have tumour promoting potential." (PMID 28578659, 2017). "In multivariate analysis, co-polysomy maintained an independent prognostic impact on survival (P=0.001) after adjustment for age, KPS, grade, removal degree, tumor size, Ki-67 index, and IDH1/2." (PMID 28978019, 2017). "IDH-1 wildtype proneural tumor is more amenable to standard treatment regimen than those presented with mesenchymal tumor subtype." (PMID 28630875, 2017). "All model system unequivocally confirmed that IDH1 R132H renders tumor cells more prone to the effects of inhibition of Bcl-xL either by siRNA or pharmacologically through the BH3-mimetic, ABT263." (PMID 29057925, 2017). "In fact, this precaution is not limited to IDH1 R132 and IDH2 R172 mutations, but should be borne in mind whenever we try to sort driver mutations from passenger ones in any type of tumor." (PMID 28785398, 2017). "These mutations make IDH1 or IDH2 lose the function of clear metabolites (2HG), resulting the accumulation of 2HG within the tumor." (PMID 28939851, 2017). "As expected with a mutant IDH1-selective compound, no tumor growth inhibition was observed following MRK-A treatment in this IDH1 wildtype tumor model." (PMID 29062039, 2017). "In our study, similar to previously reported studies, the IDH1 status of the primary tumour was consistent with that of the corresponding recurrent tumour in all cases." (PMID 29026176, 2017). "In the H3/IDH1 mutant group, ATRX mutations were observed in 3 hemispheric tumor pairs: one pair with H3G34V (HGG5), and two with IDH1 R132H/S (HGG6, HGG7) mutations." (PMID 29084603, 2017). "The strong connection between the deep information and IDH1 statuses benefited from the outstanding tumor recognition ability of the CNN." (PMID 28710497, 2017). "Compared to these methods, our team used anatomic location as basic tumor feature to predict biomarkers like IDH1/1p19q/TERT, which is more simple, cost effective and visualized." (PMID 28915860, 2017). "We propose a MassARRAY (MS)-based test that can identify 1p/19q codeletion using quantitative SNP genotyping and, simultaneously, characterize hotspot mutations in the IDH1, IDH2, and TERT genes in tumor DNA." (PMID 28915660, 2017).